CTSK (cathepsin K)
Diseases named in the same sentence as CTSK in open-access papers (continued):
Sharing a sentence is not in itself a finding about the gene and the disease.
tumor (continued). "Ultimately, we identified the CTSK + MRC2 + CAF cluster as an APPCAF cluster that interacts strongly with T cells, which may help regulate different aspects of tumor immune microenvironment (TIME) biology." (PMID 38221616, 2024). "This tumor is usually positive for Pax8, melanocytic markers (melan-A and HBM-45), and cathepsin-K." (PMID 39502747, 2024). "LAM is a low-grade neoplasm diffusely affecting the lungs of young women with a nodular and cystic pattern due to irregular interstitial growth of the perivascular epithelioid cell (PEC) system cells, expressing HMB45 and cathepsin K." (PMID 36832290, 2023). "Cathepsin K (CTSK), the lysosomal cysteine protease has a principal role in cancer invasion and progression through interaction with the tumor microenvironment, degradation of extracellular membrane proteins and destruction of the elastic lamina of blood vessels." (PMID 37198626, 2023). "In the instance of secreted cathepsin K, it could also polarize M1 macrophages to M2 through TLR-4 processing and activation, which is viewed as an important aspect of M2 macrophage–tumor cross talk for EMT progression of cancer cells." (PMID 34918208, 2022). "Conversely, expression of β-catenin and vimentin almost disappeared in the tumor regions of mice with the negative CTSK expression while the expression of E-cadherin was high." (PMID 36138018, 2022). "The study showed that CTSK can rapidly degrade the ECM and promote the metastasis of tumor cells." (PMID 36005209, 2022). "Moreover, genes representing mesodermal or/and endodermal tissue differentiation (ACP5, ACTA2, BGLAP, CTSK, DESMIN, FOXA2) were activated in tumor." (PMID 33468253, 2021). "CTSK inhibitor therapy reduced skeletal tumor burden but did not block the growth of primary tumor, indicating that CTSK generates a favorable bone microenvironment for tumor growth by promoting bone resorption." (PMID 31222004, 2019). "Similarly to the other tumours generated in this study, these allograft tumours stained positively for PMEL, CATHEPSIN K, PDGFRβ, SMA and VIMENTIN, expressed PMEL by western blotting, and exhibited a similar frequency of PMEL expressing cells." (PMID 29133867, 2017). "The presence of tumor cell-derived exosomes also clearly decreased the expression of established markers for osteoclast fusion and differentiation, including DC-STAMP, TRAP, cathepsin K, and MMP-9." (PMID 27832183, 2016). "In our patient samples, cathepsin K was present in OTSCC tumor epithelial cells, but not in normal mucosa keratinocytes." (PMID 23951042, 2013). "In conclusion, it was demonstrated that cathepsin K was immunopositive in two cases of BSCC of the maxillary sinus and that it may be involved in tumor invasion by this highly aggressive carcinoma." (PMID 23833636, 2013). "The expression of cathepsin K combined with the expression of other proteases may lead to extracellular matrix degradation and subsequent SRC tumor progression." (PMID 20809981, 2010). "By IHC and immunoblotting, STP tumor cells showed strong expression of nuclear TFE3, the canonical TFE3 target GPNMB, as well as expression of melanocytic and lysosomal markers (PMEL, MelanA and Cathepsin K) commonly upregulated in human MiT/TFE-related neoplasms." (PMID 41044182, 2025). "Immunohistochemical analysis using the recommended minimum antibody panel (CAIX, TFE3, PAX8, HMB-45 and Melan-A, Cathepsin K, AMACR, CK-7, EMA) could be advised routinely for every case of RCC, regardless of the patient′s age and the microscopic features of the tumor." (PMID 35886994, 2022). "Similarly, CTSK can promote CRC progression by promoting M2 polarization of TAM through a TLR4-mTOR-dependent pathway, while M2 macrophages can secrete chemokines such as IL7 and EGFR to activate the NFκB pathway to further promote tumor tissue invasion and metastasis." (PMID 37930479, 2023).
tumor (continued). "On the other hand, AKR1B1 (SMD = 0.3; 95% CI 0.01; 0.60; P < 0.01), CTSK (SMD = 1.52; 95% CI 0.98; 2.06; P < 0.01), MMP2 (SMD = 1.02; 95% CI 0.51; 1.53; P < 0.01), TLR4 (SMD = 0.85; 95% CI 0.34; 1.37; P < 0.01) were up-regulate in cancer groups, which might be the tumor proto-oncogene." (PMID 34646828, 2021). "In extraosseous tumours, cells in contact with malignant cells did not expressed DKK1, MCSF, cathepsin K and IL6." (PMID 18253114, 2008). "Both models exhibited the same immunohistochemical labelling pattern: tumour cells never exhibited significant labelling for M-CSF, Dkk-1, RANKL, IL-6 or cathepsin K." (PMID 18253114, 2008). "Immunohistochemically, the tumor cells were diffuse moderately or strongly positive for CD10, P504S, vimentin, PAX8, RCC, AE1/AE3, and SDHB and focally positive for CK7 and CA IX while negative for cathepsin K, HMB45, Melan-A, Ksp-cadherin, and CD117." (PMID 31828108, 2019). "(Immunohistochemical stains showed that the tumor cells were positive for desmin and TFE3, while negative for pancytokeratin, CAM5.2, EMA, chromogranin, synaptophysin, NSE, CD45, SMA, HHF35, myogenin, CD117, DOG1, MUC4, S100, SOX10, HMB45, Melan-A, CD31, ERG, TLE1, STAT6, and Cathepsin-K)." (PMID 35001360, 2022).
cancer (56 papers, 2010 to 2026). A tumor composed of atypical neoplastic, often pleomorphic cells that invade other tissues. "As we discussed in advance several studies have reported a high level of CTSK expression associated with metastasis of cancer cells." (PMID 37198626, 2023). "CTSK is associated with the activation of these signaling pathways and is arguably a novel target for cancer-induced bone resorption." (PMID 36005209, 2022). "Increasing studies have reported that the overexpression of CTSK is associated with cancer metastatic disease, indicating its potential diagnostic and prognostic value." (PMID 36005209, 2022). "CtsK expression has been associated with cancer progression and has been pharmacologically targeted in several clinical studies." (PMID 32188406, 2020). "Cathepsin B is associated in the invasion process in many types of cancer and these data confirmed the essential role of this cathepsin, in contrast to cathepsin L and cathepsin K in GBM invasion." (PMID 28424417, 2017). "Contrastingly, cathepsin K inhibition in cancer cells caused the destabilization of Raptor." (PMID 37330581, 2023). "Genes involved in cancer cell invasion, CTSK and LOXL4, were also upregulated, enhancing our observations on EMT pathway markers." (PMID 40434957, 2025). "AKR1C1+ inflammatory fibroblast significantly co-localized with cancer cells, neutrophil, CTSK+ macrophage, DC1, and PRR-induced mo-DC." (PMID 38744958, 2024). "Several other extracellular stroma-associated proteins specifically linked to CTSK, including SPARC and TNC, are reportedly highly expressed in cancer tissue and promote the invasion and metastasis of multiple cancers." (PMID 38594611, 2024). "Calcyclin-binding protein (CYBP) has been reported as a migration suppressor, and cathepsin K is well known as a positive regulator of bone resorption, cancer progress, and cancer cell migration." (PMID 36674719, 2023). "Our previous study suggested that cathepsin K inhibition enhances anti-cancer drug-induced apoptotic cell death through the upregulation of USP27x-mediated Bim pro-apoptotic protein." (PMID 37330581, 2023). "The great role of CTSK in cancer progression through triggering many signaling pathways indicates its utility as a therapeutic target for cancer treatment." (PMID 37198626, 2023). "Cathepsin K is a well-known therapeutic target in osteoclasts; however, its expression increases in cancer cells and is related to cancer metastasis." (PMID 37330581, 2023). "In preclinical or clinical studies, high CTSK expression was detected in the serum and tissues of cancer patients." (PMID 37198626, 2023). "Most recently, our previous study reported that targeting cathepsin K using siRNA or ODN enhances cancer cells’ sensitivity to sub-lethal doses of anti-cancer drugs by triggering pro-apoptotic protein Bim stabilization." (PMID 37330581, 2023). "The pharmacological and genetic inhibition of cathepsin K enhanced the sensitivity to anti-cancer drugs." (PMID 37330581, 2023). "Moderate CTSK expression was characteristically observed only in high-grade carcinomas; one case of high-grade MEC (7.7%), three cases of AdCC (25%), and two cases of CXPA (25%)." (PMID 37198626, 2023). "Low-grade carcinomas mainly presented weak CTSK expression; five cases of low-grade MEC (71.4%) and three cases of ACC (60%)." (PMID 37198626, 2023). "Clinically, some progress has been made with the use of cathepsin K inhibitors in the treatment of certain cancers." (PMID 36005209, 2022). "More importantly, CTSK is a key enzyme in the resorption process of osteoclasts and can effectively degrade type I collagen, thereby promoting the bone metastasis of cancers." (PMID 36005209, 2022). "Our aim was to systematically review the relevant roles of cathepsin K (CTSK) in various possible cancers in existing studies." (PMID 36005209, 2022).
cancer (continued). "Based on recent research findings, this article reviews the role of CTSK in various cancers, which is expected to be a potential therapeutic target." (PMID 36005209, 2022). "In preclinical or clinical studies, it was found that the high expression of CTSK was detected in the serum and tissues of cancer patients." (PMID 36005209, 2022). "Given the critical role of CTSK in bone remodeling, CTSK inhibitors should benefit the treatment of cancers characterized by extracellular matrix degradation." (PMID 36005209, 2022). "Cathepsin K acts in cancer progression and invasion by indirectly or directly degrading extracellular matrix proteins." (PMID 34785775, 2022). "Combined treatment with SM934 (a novel water-soluble artemisinin analog) and testosterone inhibited proliferation and metastasis of cancers by inhibiting cathepsin K expression, which in turn inhibited Bcl-xL." (PMID 34785775, 2022). "In order to verify that CTSK is more specific in the treatment of cancers and seek better treatment results, a large number of studies and more in-depth mechanism studies are still needed." (PMID 36005209, 2022). "CTSK has been found in different types of cancer, including PC, breast cancer, and colorectal cancer." (PMID 36138018, 2022). "In this review, we summarize our current understanding of the role of CTSK in cancer and evaluate its potential as a biomarker and/or novel therapeutic target for cancers." (PMID 36005209, 2022). "The ability of invasion and migration of PC cells, enhanced by CTSK, was in common with the pivotal role of CTSK in different types of cancer." (PMID 36138018, 2022). "According to previous researchers, it has been reported that the expression level of CTSK is higher after the metastasis of cancer cells." (PMID 36005209, 2022). "Cathepsin K (CTSK) is a lysosomal cysteine protease, which is implicated in signal transduction in cancer cells." (PMID 34326840, 2021). "Osteoclast precursors cocultured with PARP2KD cancer cells showed increased expression of osteoclast marker gene cathepsin K (CTSK)." (PMID 32221289, 2020). "High expression of cysteine proteinases and in particular of CtsK has been detected in a variety of cancer cells." (PMID 32188406, 2020). "We found that the addition of CTSK to CM from FOXF2-depleted cancer cells restored the reductions in the number and size of TRAP+ osteoclasts." (PMID 31222004, 2019). "We found that IL-20 is able to stimulate the growth, migration, and function as an upstream mediator to enhance MMP-9, MMP-12, cathepsin K, and cathepsin G secretion in cancer cells." (PMID 29690863, 2018). "The localization of cathepsin K was distinctly present in specific cells, whereas cathepsin B and X were present in most cancer cells surrounding the arterioles." (PMID 30046941, 2018). "Both cathepsin G and cathepsin K play crucial roles in tumor-induced osteolysis, and they are also potentially a novel therapeutic target for treating cancer." (PMID 29690863, 2018). "Cathepsin K is up-regulated in cancer cells that proteolyze extracellular matrix and contributes to invasiveness." (PMID 26931461, 2016). "Previous studies have demonstrated a role for cathepsin K in malignant tumors in certain organs, including the breast, skin and lungs." (PMID 23833636, 2013). "In this environment, regulation of the expression of cathepsin K between stroma and carcinoma cells appears to be far more complex and dynamic, where cathepsin K expression intensity is complementary between stromal and epithelial cells." (PMID 23951042, 2013).
cancer (continued). "Considering that these pro-tumorigenic component states (i.e., desmoplastic fibroblast, osteoblast, and CTSK+ macrophage) negatively impact immunotherapy responses across different cancer types, alternative treatment strategies should be pursued for patients with pro-tumorigenic ecosystems." (PMID 38744958, 2024). "CTSK is reportedly involved in cancer progression and invasion through TME remodelling." (PMID 38594611, 2024). "A previous study suggested that Cathepsin K might degrade extracellular membrane proteins and disrupt the elastic layer of blood vessels to promote cancer invasion and progression." (PMID 39202574, 2024). "The reversible binding mechanism of GD42 could be used for providing the exact localization of CTSK in the subcellular compartments of primary and cancer cells with the help of live cell imaging techniques." (PMID 38970171, 2024). "Therefore, the level of CTSK in cancer tissue is considered an effective index for predicting the severity and prognosis of cancers." (PMID 37198626, 2023). "CTSK has a great role in cancer progression by triggering many signaling pathways." (PMID 37198626, 2023). "Cathepsin-K is usually studied as a functional molecule related to osteoclasts, belonging to the cathepsin L-like cluster of the C1A family, elevated CTSK activity is strongly associated with the development and recurrence of metastasis in many cancers." (PMID 37930479, 2023). "Pan-cancer analysis revealed significant high expression of CTSK in a variety of cancers." (PMID 37930479, 2023). "Recently, the utility of CTSK inhibitors in cancer treatment reached some progress." (PMID 37198626, 2023). "In SGCs, CTSK was present mainly in carcinoma cells, but sometimes present in stromal cells." (PMID 37198626, 2023). "Strong CTSK expression was significantly related to high-grade SGCs (P = 0.000), large infiltrating carcinomas (P = 0.000), presence of nodal (P = 0.041) and distant metastasis (P = 0.009), advanced TNM clinical stage (P = 0.000), the incidence of recurrence (P = 0.009), and reduced DFS (P = 0.006)." (PMID 37198626, 2023). "Moreover, strong CTSK expression was significantly reported in carcinomas that had positive nodal and distant metastasis." (PMID 37198626, 2023). "Moreover, CTSK is positive in eosinophilic solid and cystic renal cell carcinomas, which are relatively rare cancers, and also similar to epithelioid angiomyolipoma." (PMID 36005209, 2022). "The inhibition of CTSK attenuates osteolytic lesions and, thus, inhibits cancer progression." (PMID 36005209, 2022). "Physiologically, CTSK functions by mediating various aspects of the extracellular matrix turnover, collagen degradation, bone resorption and remodeling of the extracellular matrix, which plays an important role in cancer." (PMID 36005209, 2022). "It is known that some biomarkers are also the therapeutic target for cancers, and searching novel CTSK inhibitors might be beneficial for the treatment and prevention of various cancers." (PMID 36005209, 2022). "In conclusion, in this review, we summarized that CTSK may be a novel cancer biomarker and therapeutic target." (PMID 36005209, 2022). "Additionally, it was also reported that CTSK can promote the proliferation and metastasis of cancer cells via activating the PAR-3 and PAR-4 receptors." (PMID 36005209, 2022). "CTSK is involved in the pathological process of cancer development, so it seems that CTSK could be also a potential therapeutic target for cancer treatment." (PMID 36005209, 2022). "Cathepsin K is highly expressed in various types of cancers." (PMID 34785775, 2022). "The CTSK levels are higher than normal after cancer metastasis, and this change might be used to diagnose and assess the severity of cancer patients." (PMID 36005209, 2022).